ALK (ALK receptor tyrosine kinase)
Diseases named in the same sentence as ALK in open-access papers (continued):
Sharing a sentence is not in itself a finding about the gene and the disease.
tumor (continued). "This gene rearrangement creates an activated ALK tyrosine kinase that leads to cell proliferation and survival, which serves as a driver for tumor formation." (PMID 39807831, 2025). "Especially in the liver, ALK+ cells were prominent around vessels, indicating a potential tumor cell dissemination through circulatory and lymphatic systems." (PMID 40175628, 2025). "FISH with an ALK break-apart probe (Vysis; Abbott, Abbott Park, IL, USA) confirmed an ALK gene rearrangement in 88% of tumor cells." (PMID 41036487, 2025). "Aberrant activation of ALK serves as a pivotal oncogenic driver in a wide range of solid tumors and hematological malignancies, broadly contributing to tumor initiation, progression, and invasiveness." (PMID 41614760, 2025). "Combined treatment with an ALK inhibitor and anti-PD-1 antibody improves tumor regression and long-term immunity." (PMID 40764998, 2025). "Higher mutation rates of ERBB4 and ALK in H/L patients suggest ethnicity-specific alterations in the RTK/RAS pathway, possibly linked to differential tumor biology or therapeutic response." (PMID 40869017, 2025). "Among the findings, the dataset highlighted significant associations between imaging features such as tumor size, texture, and [18F]FDG-PET uptake, with key oncogenic mutations (e.g., EGFR, KRAS, ALK) and survival outcomes." (PMID 40192792, 2025). "Many lines of evidence indicate that the anti-tumor immune response, which develops naturally or after immunogenic therapy, contributes to eradicate ALK-positive ALCL." (PMID 41469691, 2025). "Pre-operative ALK inhibition or chemotherapy can down-stage initially unresectable tumours, enabling R0 resection while maximally preserving adjacent organs." (PMID 40980125, 2025). "NGS of the pericardial effusion (520-gene panel, Burning Rock Biotech, Guangzhou, China)detected the original ALK rearrangement, and a novel KIF5B-RET fusion (K15:R12 allele frequency AF: 31.86%, tumor mutation burden:4.99 mutations/Mb)." (PMID 40599544, 2025). "Our analysis of publicly available RNA expression data for over 12,000 tumor samples supports nominating ALK as an exemplary lineage-restricted ADC target across multiple childhood and adult malignancies." (PMID 40813394, 2025). "Current data show the potential of RTKi not only for ALK mutant NBs, but also for the majority of NB tumours with overactivation of growth factor signalling." (PMID 41511287, 2025). "Addressing immune escape is a crucial aspect of managing ALK-targeted therapy resistance, and treatment strategies must consider tumor characteristics, patient condition, therapeutic efficacy, and safety." (PMID 40873540, 2025). "We acquired 14 different FFPE tumor samples where prior analysis had indicated that ALK or NTRK fusion status was positive." (PMID 39773366, 2025). "•When the patient experienced resistance to crizotinib, alectinib immediately relieved the patient's symptoms and controlled most of the lesions, suggesting that the relapsed tumor is still ALK-driven." (PMID 40054123, 2025). "While high expression is desirable for the success of chimeric antigen receptor (CAR) T cell therapies, our data demonstrates robust and sustained anti-tumor activity in models with modest ALK expression levels." (PMID 40813394, 2025). "For instance, the spatial and temporal heterogeneity of actionable mutations in genes like ALK and FGFR1 can compromise the accurate assessment of a tumour’s susceptibility to targeted inhibitors." (PMID 41511287, 2025). "Amplifications in the ALK, DYNC1I1, and TRRAP genes were found in one tumor, which also showed a point mutation in TERT (each 5%)." (PMID 40227833, 2025). "Second‐generation TKIs, such as afatinib, and ALK inhibitors, such as alectinib, have addressed this issue by irreversibly blocking their respective receptors, resulting in improved tumor control." (PMID 41245887, 2025).
tumor (continued). "The first-generation ALK inhibitor crizotinib competitively binds to the ATP-binding site of the kinase domain, and inhibits tumor growth by blocking the downstream signaling pathway." (PMID 41472727, 2025). "Mutations in canonical oncogenes such as BRAF, KRAS, PIK3CA, and ALK function as dominant molecular drivers, defining biologically distinct tumor subsets characterized by specific therapeutic liabilities." (PMID 41228293, 2025). "The EML4-ALK fusion gene leads to the aberrant activation of ALK kinase, thereby facilitating the growth and proliferation of tumor cells." (PMID 40584293, 2025). "Targeting the RNase1/ALK axis reprograms TAMs, enhances T cell recruitment, and restores anti-tumor immunity." (PMID 40764998, 2025). "Regarding known tumor drivers in NSCLC and response to ICB, there are some data where tumors driven by EGFR variants and ALK rearrangement have been shown to be resistant to ICB regardless of PD-L1 expression status." (PMID 40011914, 2025). "These strategies, along with other rational combination regimens, are being explored to enhance tumor immunogenicity and overcome the inherently “cold” immune landscape characteristic of ALK-rearranged NSCLC." (PMID 40894217, 2025). "The patient received initial chemotherapy, surgery, and an ALK tyrosine kinase inhibitor (lorlatinib), which led to a reduction in tumor size and a partial response." (PMID 41007824, 2025). "Circulating tumor DNA (ctDNA) is evolving into a promising non-invasive approach for the detection of ALK rearrangement." (PMID 40853979, 2025). "Data from this study suggest that ALK fusions have a negative prognostic effect in metastatic solid tumors and highlight the need for further investigation of ALK inhibitors in the tumor-agnostic setting." (PMID 40338218, 2025). "Another challenge in treating ALK‐positive NSCLC is the persistence of the residual disease at the primary tumor sites in the lung." (PMID 41213866, 2025). "These rearrangements lead to constitutive activation of ALK signaling, which promotes cell proliferation and tumor growth." (PMID 40168046, 2025). "Collectively, these preclinical studies in several xenograft models with different ALK aberrations demonstrate that ESK440 treatment significantly impacts tumor growth kinetics in ALK-driven NB models." (PMID 39900433, 2025). "Anti-ALK antibody titer in serum or plasma is a surrogate marker of the strength of a specific anti-tumor immune response orchestrated by T lymphocytes and mediated by B cells." (PMID 41469691, 2025). "What stands out is that these pan-tumour drugs are also amenable to targeted therapy for mutations like EGFR and ALK." (PMID 39212880, 2025). "Here, we first confirm that ALK RNA, protein, and tumor cell surface expression is elevated in multiple pediatric and adult malignancies with minimal expression in childhood normal tissues." (PMID 40813394, 2025). "In contrast, tumor spheroids treated with CAF-CM accumulated fewer lipid peroxides despite the inhibition of ALK." (PMID 40524253, 2025). "Ceritinib, a second generation ALK inhibitor, was initially described for its potent and selective anti-tumor effects, with nanomolar efficacy in cellular assays." (PMID 40968384, 2025). "Patient-derived xenograft mouse model showed, RDAA positive tumor were sensitive to ALK inhibitor crizotinib treatment." (PMID 40246819, 2025). "Tumor tissues were harvested 4 h after the last treatment, and activation states of ALK and FAK were evaluated using immunohistochemistry (IHC) and western blotting." (PMID 39900433, 2025). "Immune escape contributes to the development of resistance to ALK-targeted therapies by allowing tumor cells to avoid recognition and clearance by the immune system through multiple mechanisms." (PMID 40873540, 2025). "Of the two patients who received ALK‐TKIs, one had the tumor removed surgically after targeted therapy, while the other was progression‐free for 30 months." (PMID 41262926, 2025).
tumor (continued). "Among these, IMT is a common type of intermediate (locally aggressive) tumor composed of myofibroblasts, frequently harboring ALK or ROS1 fusions." (PMID 40242239, 2025). "The genomic landscape of Spitz neoplasms includes fusions in genes such as ALK, ROS1, MET, RET, or BRAF and mutations in HRAS genes, which influence both the tumor’s biological behavior and morphological features." (PMID 40870546, 2025). "In cases of suspected CD117-negative GIST, a panel of markers, including DOG1, CD34, S-100, SMA, CD21, ALK, and desmin, should be used to differentiate this tumor from gastric CFTs." (PMID 40356746, 2025). "This protein has a major role modulating the tumor microenvironment, and fragments loaded into exosomes of pediatric ALK+ ALCL patients correlated with more advanced and aggressive disease." (PMID 40565334, 2025). "Intriguingly, the first‐in‐class PTPN2/N1 inhibitor AC484 shows a great anti‐tumor effect against ALK+ ALCL, providing a rationale for conducting clinical trials of AC484 on ALK+ ALCL patients." (PMID 40734623, 2025). "Compared with those treated with chemotherapy, individuals treated with ALK-targeted agents live longer, experience more significant tumor shrinkage, and display an increased period of continued symptom deterioration." (PMID 40071084, 2025). "Compared with other tumor genotypes, ALK-rearranged tumors exhibit more invasive histomorphological features and aggressive behaviors." (PMID 40376302, 2025). "The findings from this study are expected to provide insights into the primary resistance mechanisms, thereby improving our understanding of how tumor microenvironment dynamics contribute to treatment outcomes in ALK-positive NSCLC." (PMID 40563563, 2025). "EFS and OS for patients with any ALK-aberrant tumor were inferior to patients with wild-type (WT) ALK tumors (5-year OS 37.7% v 66.3%; hazard ratio [HR], 1.992; P = .0007)." (PMID 40036726, 2025). "Considering the tumor’s location, adjuvant chemotherapy and the ALK inhibitor Crizotinib were initiated, and, as of the last follow-up, the patient was still living with the disease." (PMID 40260197, 2025). "Targeted therapies improve survival by addressing mutations like EGFR, ALK, ROS1, and KRAS but face resistance, bypass signaling, and tumor heterogeneity." (PMID 41476609, 2025). "Alectinib is a targeted therapy drug used majorly to treat NSCLC patients whose tumours are anaplastic lymphoma kinase (ALK)-positive." (PMID 39766122, 2024). "Still, the perception remained that Pemetrexed should be used when treating patients with ALK-translocated tumours." (PMID 38610927, 2024). "Switching to lorlatinib allowed continuation of ALK inhibitor therapy, resulting in tumor reduction and improved liver function." (PMID 39527462, 2024). "The 16 articles included a total of 55 cases, in which the primary, intracranial ALK-positive or ALK-altered tumor was located in the posterior fossa (brainstem, pons, cerebellum, or cerebellopontine angle-CPA)." (PMID 38339401, 2024). "Early co-targeting of ALK and MEK showcased improved responses and delayed resistance in preclinical ALK+ tumor models, proposing a hopeful approach to enhance the treatment of ALK+ patients." (PMID 38397899, 2024). "When we injected mice with BEAS-2B where a single DSB was introduced in ALK intron 19, we observed tumor formation at a lower rate and with a slower growth kinetics." (PMID 38877018, 2024). "In ALK-independent resistance, tumor cell proliferation relies on alternative ALK-independent pathways." (PMID 39457620, 2024). "IHC staining of the tumor and matched normal lung organoids showed ALK staining in tumor organoids and the corresponding primary tissue." (PMID 38528665, 2024).
tumor (continued). "In, 2016, the FDA approved Atezolizumab as a therapy for patients with metastatic NSCLC who have experienced disease progression during or following platinum-containing chemotherapy, and if their tumor has EGFR or ALK gene abnormalities." (PMID 38384472, 2024). "In fact, the histological profile of tumours harbouring ROS1 or ALK translocation is very similar, featuring the presence of signet ring cells." (PMID 38793028, 2024). "Taken together, these T cytotoxicity efficacy results suggest the potential of our ALK-targeting VH20 to be used in the context of bispecific T cell engager for the eradication of ALK-positive tumor cells." (PMID 38804307, 2024). "Due to its success in the preclinical setting with different ALK fusion partners, EML4 variants, and tumor contexts, NVL-655 is undergoing further evaluation in the phase I/II ALKOVE-1 trial (NCT05384626)." (PMID 38835344, 2024). "ALK gene rearrangements in tumor specimens can be identified using immunohistochemistry (IHC), reverse transcription polymerase chain reaction (RT-PCR) of cDNA, and FISH." (PMID 39335535, 2024). "der inflammatorische myofibroblastäre Tumor, wird die ALK-positive Histiozytose vorrangig bei weiblichen Individuen beobachtet." (PMID 38602523, 2024). "The identification of ALK rearrangements in other tumor types has subsequently gained importance owing to the availability of ALK inhibitor-targeted therapies." (PMID 39205743, 2024). "Immunohistochemistry for ALK demonstrated diffuse positive expression of ALK in the tumor cells, with a distinctive nuclear membranous staining pattern." (PMID 39871941, 2024). "Nevertheless, the wide use of second-generation ALK inhibitors can inevitably lead to drug resistance and tumor relapse, which can also be divided into ALK-dependent mechanisms and ALK-independent." (PMID 38655260, 2024). "Our study demonstrates a link between activation of ALK and tumor growth via increased ECM production and activation of the WNT pathway." (PMID 38451815, 2024). "RNase1 induces the polarization of macrophages towards a tumor growth-promoting phenotype through activation of the anaplastic lymphoma kinase (ALK) signaling pathway." (PMID 38307859, 2024). "Crizotinib has demonstrated significant efficacy in reducing tumor size by approximately 50% to 60% in patients with ALK protein alterations, even among those previously treated with chemotherapy." (PMID 38397899, 2024). "The immunophenotype of tumor cells includes strong ALK expression (ALK gene rearrangement) and expression of plasma-cell markers CD38, CD138, and VS38C." (PMID 39906668, 2024). "ALK-dependent resistance hinders the binding of the drug to the active site and approximately one-third of ALK-positive tumours treated with crizotinib develop some of these alterations." (PMID 38793028, 2024). "The importance of performing liquid biopsies and detecting circulating tumor cells (CTCs) in NSCLC is crucial for identifying activating genetic mutations, such as ALK (anaplastic lymphoma kinase) rearrangements." (PMID 39064229, 2024). "The most affected oncogenic signaling pathways in our NB tumor samples were RTK-RAS, NOTCH, and Hippo, which are linked to primary mutations in ALK, NCOR2, and FAT2, respectively." (PMID 39338204, 2024). "Generally, the presence of ALK rearrangement in cancer cells has the potential to influence the dynamics of interactions between tumor and immune cells." (PMID 38397899, 2024). "Just recently, an ADC targeting the receptor kinase anaplastic lymphoma kinase (ALK) was shown to be highly effective in patient-derived ALK-high tumor models." (PMID 39065640, 2024). "Both VH20-based bispecific T cell engager (TCE) and chimeric antigen receptor T cells (CAR Ts) exhibited potent cytolytic activity to ALK-expressing tumor cells in an ALK-dependent manner." (PMID 38804307, 2024).
tumor (continued). "Cell viability assays using CellTiter‐Glo reagents showed that Gal9‐KO significantly sensitized tumor organoids harboring ALK translocation to crizotinib (organoid #2) or those with KRAS mutations (organoid #3) to cisplatin." (PMID 38528665, 2024). "Ten ALK-positive NSCLC patients and 17 ALK-negative NSCLC patients were included, and the immunohistochemical staining results showed that TF was predominantly expressed at the tumor site in ALK-positive NSCLC." (PMID 37940761, 2024). "CD68 and CD163 expression varied across tumor sections, with some showing strong positivity and others resembling atypical ALK-rearranged histiocyte-rich tumors." (PMID 39867882, 2024). "Next, we compared the activity levels of WNT and YAP signaling in ALK/MYCN tumor cells with control single guide RNA (sgRNA) or POSTN sgRNA." (PMID 38451815, 2024). "This drug demonstrates promising potential in inhibiting c-MET and ALK phosphorylation, curbing tumor cell growth, exhibiting antiangiogenic properties, and inducing apoptosis in specific cancer cells." (PMID 38397899, 2024). "In one study, NSCLC patients with ALK fusion showed EGFR gene activation in 44% of tumor samples after developing resistance to ALK TKI crizotinib." (PMID 39582541, 2024). "The findings highlight the complex interplay between genomic alterations, the tumor immune microenvironment, and clinical outcomes in ALK/RET/ROS1-rearranged NSCLC using NGS." (PMID 38397899, 2024). "Although these markers had not been previously shown as prognostic in HL, there is literature showing ADA and its ligand CD26 as higher in ALK-positive NHL and HL as well as being associated with poor outcomes in other tumor types." (PMID 38934093, 2024). "Factors such as ALK rearrangements and EGFR mutations, patient-specific characteristics, genetic changes, treatment modalities, and tumor heterogeneity significantly impact the disease's progression and response to therapy, thereby affecting survival rates." (PMID 39850198, 2024). "Despite the predictive effect of the PD-L1 biomarker, there are still several limitations to its practical use, including variation over time and tumor locations, inconsistent prediction efficacy, and unclear interactions with EGFR and ALK mutations." (PMID 39350284, 2024). "Several ALK inhibitors have demonstrated potent anti‐tumour efficacy against ALK‐mutant NB, with most of these inhibitors entering early phase paediatric clinical trials." (PMID 39501501, 2024). "Crizotinib effectively inhibits ALK and c-Met phosphorylation in a concentration-dependent manner in cell-based assays using tumor cell lines." (PMID 39335535, 2024). "Anaplastic lymphoma kinase (ALK) regulates the function of the frontal cortex and hippocampus of the adult brain as well as influences tumor cell cycle control, thus impacting tumor transformation." (PMID 39544292, 2024). "Tumor cells with on-target resistance retain their dependence on ALK, while those with off-target resistance utilize alternative ALK-independent pathways to support proliferation." (PMID 38835344, 2024). "In association with SMARCA4 mutations and clinico-genomic biomarkers across two different studies, tumor mutational burden (TMB) and brain metastasis in Anaplastic Lymphoma Kinase (ALK)-positive NSCLC were evaluated." (PMID 39063938, 2024). "Inhibition of ALK activity has been shown in many experimental systems to reduce ALK-driven NB cell and tumor growth." (PMID 38858548, 2024). "Treatment utilizing both an ALK inhibitor and an anti-PD-1 antibody exhibits enhanced tumor regression and facilitates long-term immunity." (PMID 38307859, 2024). "Strong antitumor effects have been demonstrated in tumor xenograft models derived from genetically engineered cells overexpressing ALK rearrangements, ROS1+ rearrangements, or crizotinib-resistant ALK and ROS1 mutations, as well as in CNS tumor models." (PMID 39081957, 2024).